BTG3-AS1 (BTG3 antisense RNA 1)
Synonyms: ASBEL
Gene: Long non-coding RNA gene on chromosome 21 (17,611,691 to 17,643,997, forward strand). Ensembl gene ENSG00000280594.
Diseases named in the same sentence as BTG3-AS1 in open-access papers:
BTG3-AS1 is named in the same sentence as 2 diseases in open-access papers, as found by Europe PMC text mining. Sharing a sentence is not in itself a finding about the gene and the disease.
BTG3-AS1 shares sentences with these, for which no sentence is quoted: tumor (4 papers); cancer (1).